EDAR (ectodysplasin A receptor)
Description:
Receptor for EDA isoform A1, but not for EDA isoform A2. Mediates the activation of NF-kappa-B and JNK. May promote caspase-independent cell death.
Synonyms: DL; ED5; EDA3; ED1R; EDA1R; ECTD10A; ECTD10B; ED3; EDA-A1R; HRM1
Tractability: Antibody: its Gene Ontology location is reachable by antibodies, with high confidence; UniProt predicts a signal peptide or a membrane-spanning region.
Target class: Membrane receptor
Gene: Protein-coding gene on chromosome 2 (108,894,471 to 108,989,372, reverse strand). Ensembl gene ENSG00000135960.
Subcellular location: Membrane
Pathways (Reactome):
Immune System: TNFs bind their physiological receptors
Gene Ontology:
Molecular function: protein binding; transmembrane signaling receptor activity; signaling receptor activity
Biological process: cytokine-mediated signaling pathway; epidermis development; positive regulation of canonical NF-kappaB signal transduction; positive regulation of JNK cascade
Cellular component: membrane; plasma membrane; apical part of cell
Genetic constraint (gnomAD): Loss-of-function variants: 38 observed, 53.76 expected, observed/expected ratio (o/e) 0.71, 90% interval 0.55 to 0.93. The upper end of that interval is the gene's LOEUF score, 0.93, which puts it in group 3 of 6, group 1 being the genes least tolerant of losing a copy. Missense variants: 528 observed, 616.05 expected, observed/expected ratio (o/e) 0.86, 90% interval 0.8 to 0.92. Synonymous variants: 227 observed, 249.05 expected, observed/expected ratio (o/e) 0.91, 90% interval 0.82 to 1.02.
Homologues: Orthologues: chimpanzee EDAR (100% identical), macaque EDAR (99% identical), dog EDAR (93% identical), rabbit EDAR (92% identical), mouse Edar (92% identical), rat Edar (91% identical), guinea pig EDAR (90% identical), pig EDAR (85% identical), tropical clawed frog edar (76% identical), zebrafish edar (67% identical). Paralogues in human: TNFRSF19 (20% identical), EDA2R (14% identical).
Diseases named in the same sentence as EDAR in open-access papers:
EDAR is named in the same sentence as 51 diseases in open-access papers, as found by Europe PMC text mining. Sharing a sentence is not in itself a finding about the gene and the disease. The quoted sentences say what the papers report.
ectodermal dysplasia (24 papers, 2008 to 2024). "Overall, there were clear though mild features of ectodermal dysplasia, and EDAR (MIM: 604095) variants had been excluded prior to recruitment to the 100kGP." (PMID 38776926, 2024). "This is a first case report of a patient with hypohidrotic ectodermal dysplasia from Oman, who was found to carry a mutation in the EDAR gene after candidate gene selection based on regions of homozygosity in his genome." (PMID 32274043, 2020). "The homozygous and heterozygous mutations in the EDAR death domain cause hypohidrotic ectodermal dysplasia (MIM #614940, #614941) with low penetrance." (PMID 33329022, 2020). "Four genes (EDA1, EDAR, EDARADD and WNT10A) account for 90 % of hypohidrotic ectodermal dysplasia cases and mutation in EDAR have been reported to account for 25 % of non-EDA1 HED cases." (PMID 26336973, 2015). "Mutations in the EDAR-gene cause hypohidrotic ectodermal dysplasia with defects in ectodermal appendage development including teeth, skin, exocrine glands and hair." (PMID 26336973, 2015). "Mutations in the EDAR-gene cause hypohidrotic ectodermal dysplasia, however, the oral phenotype has been described in a limited number of cases." (PMID 24884697, 2014). "The EDA/EDAR pair mediates signals needed for the development of ectodermal appendages and mutations in both genes result in hypohidrotic ectodermal dysplasia." (PMID 20807397, 2010). "Altered NF-κB signaling during development can lead to mild features of ectodermal dysplasia, such as conical teeth, which are likely due to impaired ectodysplasin A receptor (EDAR) signaling in these patients." (PMID 35289316, 2022). "Mutation of genes encoding the ligand EDA, its transmembrane receptor EDAR and the intracellular signal transducer EDARADD leads to hypohidrotic ectodermal dysplasia, characterised by impaired development of teeth and hair, as well as cutaneous glands." (PMID 35107126, 2022). "Such an ectodermal dysplasia syndrome is reminiscent of similar phenotypes in other vertebrates because of impairments of the EDA receptor (EDAR; a member of the TNF family) or its ligand EDA, indicating a conserved role of this pathway in reptiles as well." (PMID 28439533, 2016). "Only four genes (EDA1, EDAR, EDARADD, and WNT10A) account for 90% of hypohidrotic/anhidrotic ectodermal dysplasia cases." (PMID 38347173, 2024). "Four genes (EDA, EDAR, EDARADD, WNT10A) account for 90% of hypoidrotic/anhidrotic ectodermal dysplasia cases." (PMID 34078430, 2021). "Four genes (EDA1, EDAR, EDARADD, and WNT10A) account for 90% of hypohidrotic/anhidrotic ectodermal dysplasia cases." (PMID 24884697, 2014). "Genetic testing ruled out mutation of the ectodermal dysplasia-associated genes EDA, EDAR and EDARRAD11." (PMID 28589954, 2017). "Although mutation of the dl protein/ectodysplasin receptor (EDAR) induces hypohidrotic ectodermal dysplasia, TRAF6 does not bind to the cytoplasmic region of EDAR." (PMID 33840674, 2021).
hypohidrotic ectodermal dysplasia (24 papers, 2006 to 2026). A genetic disorder of ectoderm development characterized by malformation of ectodermal structures such as skin, hair, teeth and sweat glands. "Patients with mutations in the ectodysplasin receptor signalling pathway genes – the X-linked ligand ectodysplasin-A (EDA), the receptor EDAR or the receptor adapter EDARADD – have hypohidrotic ectodermal dysplasia (HED)." (PMID 31028034, 2019). "In most of the previous studies, EDAR mutations were found to be the cause of hypohidrotic ectodermal dysplasia." (PMID 28981473, 2017). "Moreover, seven nonsynonymous substitutions in the death domain of EDAR cause hypohidrotic ectodermal dysplasia (HED) in humans, a disease characterized by sparse and thin hair, missing teeth and the absence of sweat glands (OMIM∶604095)." (PMID 18493316, 2008). "Hypohidrotic ectodermal dysplasia (HED, OMIM 224900) is a rare autosomal recessive syndrome resulting from germline mutations in any of the EDA, EDAR or EDARADD genes in humans." (PMID 36699680, 2022). "Mutations in any of EDA, EDAR, and EDARADD can contribute to hypohidrotic ectodermal dysplasia (HED), which affects 1 in 10,000–100,000 newborns." (PMID 34938205, 2021). "Hypohidrotic ectodermal dysplasia (HED) represents one of the major types of EDs and is due to mutations in the EDA (MIM *300451), EDAR (MIM *604095) and EDARADD (MIM *606603) genes." (PMID 25662550, 2015). "One of the most well-characterized forms is hypohidrotic ectodermal dysplasia (HED), typically caused by variants in EDA (ectodysplasin A), EDAR (ectodysplasin A receptor), or EDARADD (EDAR-associated via death domain), and is defined by hypohidrosis, oligodontia with conical teeth, and sparse hair." (PMID 40428341, 2025). "As members of the EDA/EDAR/NF-κB signaling pathway, mutations in these genes have been implicated in the pathogenesis of NSTA, as well as hypohidrotic ectodermal dysplasia (HED), a rare genetic disorder that affects multiple ectodermal structures, including teeth." (PMID 37077539, 2023). "Mutations in the genes EDA1 receptor (EDAR) or EDARADD which underlie genetic deficiencies of the EDAR and its associated death domain-containing adaptor protein, respectively, lead to autosomal recessive or dominant hypohidrotic ectodermal dysplasia." (PMID 34456978, 2021). "X-linked hypohidrotic ectodermal dysplasia (XLHED) is the most common subtype, with an incidence of 1/50,000–100,000 males, and is associated with the EDA gene (Xq12-q13.1); the dominant and recessive subtypes involve the EDAR (2q13) and EDARADD (1q42.3) genes, respectively." (PMID 31796081, 2019). "Human patients with hypohidrotic ectodermal dysplasia (HED) have developmental defects in teeth, hair and salivary glands caused by mutations in EDA, EDAR or EDARADD." (PMID 27590203, 2016). "In humans, mutations in the genes encoding EDA, EDAR, or the cytosolic signal mediator EDARADD cause a condition known as hypohidrotic ectodermal dysplasia (HED)." (PMID 26581094, 2015).
tooth agenesis (10 papers, 2013 to 2023). A tooth disease characterized by failure to develop one or more missing teeth. "This allowed us to expand the EDAR mutation spectrum as well as providing a genetic basis for the pathogenesis of congenital tooth agenesis." (PMID 33943035, 2021). "Mutations in several genes have been associated with familial tooth agenesis, among others MSX1, PAX9, AXIN2, EDA, EDARADD, and EDAR." (PMID 33743023, 2021). "Causative variants in genes of the EDA/EDAR/NF‐κB pathway, such as EDA and EDARADD, have been widely identified in patients with non‐syndromic tooth agenesis (NSTA)." (PMID 33943035, 2021). "In this study, we investigated the contribution of WNT10A, EDA, EDAR and EDARADD mutations in patients with isolated or syndromic tooth agenesis." (PMID 24312213, 2013). "This study verifies the fact, collected by other authors around the world, that pathogenic variants in WNT10A, EDAR, and EDA are the most frequently known causes of autosomal recessive hypodontia/oligodontia, autosomal recessive HED, X-linked HED, and X-linked isolated tooth agenesis." (PMID 31652981, 2019). "However, among those 119 sequence variants a c.956G>T mutation in X-linked EDA1 was the unique one among six candidate genes (viz.PAX9, MSX1, AXIN2, WNT10A, EDAR and EDA1) associated with non-syndromic tooth agenesis known so far." (PMID 25203534, 2014). "Of these, EDA, EDAR, EDARADD, and WNT10A are candidate genes of both non‐syndromic tooth agenesis and syndromic tooth agenesis (STA)." (PMID 33943035, 2021). "WNT10A, EDA, EDAR and EDARADD were sequenced in 88 patients with isolated oligodontia and 26 patients with syndromic tooth agenesis." (PMID 24312213, 2013).
Oligodontia (8 papers, 2009 to 2024). The absence of six or more teeth from the normal series by a failure to develop. "The identified novel missense variants in WNT10A (c.311G>A; p.Arg104His) and EDAR (c.1300T>G; p.Trp434Gly) are assumed to cause autosomal recessive oligodontia and autosomal recessive HED." (PMID 31652981, 2019). "We have identified a novel missense variant (c.311G>A; p.Arg104His) in WNT10A in three oligodontia patients of family A, two novel sequence variants (c.207delinsTT, p.Gly70Trpfs*25 and c.1300T>G; p.Try434Gly) in EDAR in three patients of family B and four patients of family C, respectively." (PMID 31652981, 2019). "Missense variants (c.1138A>C) and (c.511C>T) in EDAR and WNT10A, respectively, have been previously reported in oligodontia patients." (PMID 37745851, 2023). "We found a missense variant in AXIN2, but detected no pathogenic variants in MSX1, PAX9, EDA, EDAR, or EDARADD, genes that previously have been found in nonsyndromic oligodontia." (PMID 32234057, 2020).
breast carcinoma (4 papers, 2022 to 2023). "The role of EDAR signalling in tumour development has received little attention, despite its ability to activate NFκB and the clear association of NFκB signalling with many different cancer types, including breast cancer." (PMID 34916592, 2022). "The action of EDAR in breast tissue, its similarity to the known mammary oncogene RANK, and its ability to activate NFκB, led us to investigate whether EDAR could be a causative factor in human breast cancer." (PMID 34916592, 2022). "Thus in both human and mouse increased EDAR expression is associated with this distinct mammary tumour type." (PMID 34916592, 2022). "Elevated EDAR signalling, together with activation of β-catenin activity through somatic mutation, appears to be a sufficient oncogenic stimulus to explain the high frequency of mammary tumours in the EdarTg951/951 line." (PMID 34916592, 2022). "Thus elevated EDAR expression is associated with squamous metaplasia in human breast cancers." (PMID 34916592, 2022). "A total of 16 genes were identified to be related to radiotherapy response, and low expression of SVOPL, EDAR, GSTA1, and ABCA13 was associated with poor overall survival and progression-free survival in breast cancer cases." (PMID 36896338, 2023). "We first analysed expression of EDAR in a meta-dataset of 1107 invasive human breast cancers classified into the basal-like, luminal A, luminal B, normal breast-like, and HER2 molecular subtypes." (PMID 34916592, 2022). "Moreover, univariate cox analysis indicated that only four of them (SVOPL, EDAR, GSTA1, and ABCA13) were associated with the overall survival (OS) of breast cancer patients." (PMID 36896338, 2023). "Thus, EDAR, as a newly identified death receptor oncogene, may regulate breast cancer progression, possibly by interacting with the WNT pathway." (PMID 36012178, 2022). "In conclusion, we identified that SVOPL, EDAR, GSTA1, and ABCA13 are potential prognostic biomarkers of patients with breast cancer undergoing chemoradiotherapy." (PMID 36896338, 2023). "Surprisingly, a recent study suggests that EDAR is robustly expressed in human breast cancers and its elevation induces the expression of multiple genes in the WNT pathway, which is highly correlated with breast cancer." (PMID 36012178, 2022). "Here we report that human Oestrogen Receptor (ER) negative breast carcinomas which display squamous differentiation express EDAR strongly." (PMID 34916592, 2022).
hypohidrosis (4 papers, 2009 to 2025). diminished sweating in response to appropriate stimuli. "EDA1-Gly176Val, although associated with relevant hypohidrosis, still bound to the EDA receptor (EDAR)." (PMID 35923710, 2022). "We used targeted next generation sequencing to study EDA, EDAR, EDARADD, and WNT10A genes in 45 Egyptian ED patients with or without hypohidrosis." (PMID 34573371, 2021).
melanoma (3 papers, 2020 to 2022). A malignant, usually aggressive tumor composed of atypical, neoplastic melanocytes. "EDAR therefore appears to be an atypical TNFR that induces cell death in melanoma in a receptor-dependent manner." (PMID 36012178, 2022). "Evidence has shown that EDAR knockout mice tend to develop melanoma lesions over the first 400 days, a phenotype correlating with a lower survival rate." (PMID 36012178, 2022). "In an EDAR conditional knockout mouse model, data show that EDAR inhibits the progression of melanoma, which is a highly malignant tumor of melanocytes that occurs in the skin." (PMID 36012178, 2022). "Some studies have shown that EDAR expression is markedly repressed in cutaneous melanoma samples, suggesting that EDAR may be a negative regulator for melanoma." (PMID 36012178, 2022). "Given the pro-apoptotic function of EDAR only with no EDA-A1 binding, inhibition of the expression of EDA-A1 or its interaction with EDAR may be a new method for the treatment of melanoma." (PMID 36012178, 2022). "Therefore, JAK3 may function together with BRMS1 and EDAR to suppress the migration and invasion of melanoma cells." (PMID 32051510, 2020). "Our results highlight the distinct proteomic immune signatures, such as an upregulation of EDAR and downregulation of LAG3, in responders among VLD melanoma patients in comparison to non-responders." (PMID 36230498, 2022).
Anhidrotic ectodermal dysplasia (2 papers, 2009 to 2022). "The ectoderm-derived epithelial cells express the EDAR, and a hinderance to the EDA-EDAR signaling pathway leads to genetic disorders such as anhidrotic ectodermal dysplasia." (PMID 36555342, 2022).
bipolar disorder (1 paper, 2025). A disorder of the brain that causes unusual shifts in mood, energy, activity levels and the ability to carry out day-to-day tasks. "In bipolar disorder, we identified common oligodendrocyte-specific differentially acetylated peaks in the vicinity of AP1S2, SIL1, and EDAR, while controlling for CHAS scores and MF proportions, respectively." (PMID 40300607, 2025).
colorectal cancer (1 paper, 2022). A primary or metastatic malignant neoplasm that affects the colon or rectum. "The Cancer Genome Atlas (TCGA) database has revealed an elevated expression of EDAR in colorectal cancer tissues compared to normal tissues and this pattern was confirmed by pathological analysis of patient tissues." (PMID 36012178, 2022). "Given that upregulated EDAR is involved in the occurrence and development of colorectal cancer, effective methods detecting EDAR levels in tissues of patients may provide a potential biomarker for the diagnosis of colorectal cancer." (PMID 36012178, 2022). "In addition, the high expression level of EDAR may be positively correlated with the classification, pathological stage, and poor prognosis of colorectal cancer." (PMID 36012178, 2022).
COVID-19 (1 paper, 2021). A disease caused by infection with severe acute respiratory syndrome coronavirus 2. "In support of histological evidence of lung epithelium damage, concentrations of cell death–related proteins tumor necrosis factor–α (TNFα), caspase 8, TRAIL, EDAR, and NCR1 were altered in plasma from patients with COVID-19 relative to normal controls." (PMID 34648357, 2021).
dysplasia (1 paper, 2019). A usually neoplastic transformation of the cell, associated with altered architectural tissue patterns. "Hypohidrotic ectodermal dysplasia genes, including EDA, EDAR and EDARADD, were analyzed using next-generation sequencing (NGS)." (PMID 31452656, 2019).
lung carcinoma (1 paper, 2022). "Notably, Soraas and Stebbing also revealed a positive correlation between EDAR polymorphism and EGFR mutation frequencies, showing that the EDAR gene is possibly linked with lung cancer and may have potential as a diagnostic biomarker for this disease." (PMID 36012178, 2022).
malaria (1 paper, 2012). Malaria is a serious and sometimes fatal disease caused by a parasite that commonly infects a certain type of mosquito which feeds on humans. "HDIs contain several candidate genes for local adaptation identified in previous studies, such as TRPV6, ASPM, prodynorphin [PDYN;], the duffy blood group locus involved in malaria resistance [DARC;], or the ectodysplasin A receptor [EDAR;]." (PMID 22439654, 2012).
Nail dystrophy (1 paper, 2019). Onychodystrophy (nail dystrophy) refers to nail changes apart from changes of the color (nail dyschromia) and involves partial or complete disruption of the various keratinous layers of the nail plate. "EDAR and EDARADD mutations would cause a clinically indistinguishable phenotype, but are inherited as autosomal, and WNT10A also causes a distinct phenotype with nail dystrophy." (PMID 30397018, 2019).
nasopharyngitis (1 paper, 2019). An inflammatory process that affects the nasopharynx. "We report that prenatal administration of agonist anti-EDAR antibody to EdaTa mice rescues rhinitis, nasopharyngitis, auditory-tube SMGs and otitis media." (PMID 31028034, 2019). "We report that prenatal correction of EDAR signalling in EdaTa mice with the agonist anti-EDAR antibody rescues the auditory-tube submucosal glands and prevents otitis media, rhinitis and nasopharyngitis." (PMID 31028034, 2019).
otitis externa (1 paper, 2022). Inflammation of the anatomical structures of the outer ear and ear canal secondary to an infectious process. "EdaTa mice have 25% prevalence of otitis externa at postnatal day 21 and treatment with agonist anti-EDAR antibodies rescues Zymbal’s glands." (PMID 35107126, 2022). "Additionally, otitis externa was absent in P79-P90 EdaTa mice (untreated, and those administered agonist anti-EDAR or isotype antibodies)." (PMID 35107126, 2022).